RN7SKP290 (RN7SK pseudogene 290)
Gene: Miscellaneous RNA gene on chromosome X (12,614,003 to 12,614,197, reverse strand). Ensembl gene ENSG00000271814.
Homologues: Orthologues: mouse Gm56090 (53% identical). Paralogues in human: RN7SKP113 (70% identical), RN7SKP50 (70% identical), RN7SKP214 (69% identical), RN7SKP149 (67% identical), RN7SKP47 (63% identical), RN7SKP203 (61% identical), 7SK (61% identical), RN7SKP180 (61% identical), RN7SKP217 (61% identical), RN7SKP225 (61% identical), RN7SKP171 (60% identical), RN7SKP239 (60% identical), and 284 more.